CDKN2A (cyclin dependent kinase inhibitor 2A)
Diseases named in the same sentence as CDKN2A in open-access papers (continued):
Sharing a sentence is not in itself a finding about the gene and the disease.
cancer (continued). "CDKN2A gene expression has been reported to be influenced by the SNP rs11515, which is the most frequent CDKN2A polymorphism located in the 3′UTR of the gene and has been associated with various cancers." (PMID 31916407, 2020). "For the cancer types that performed the worst, liver hepatocellular carcinoma included none of the used oncogenes (AR, KLF4, PDGFRA, and RET) or tumor suppressors (BRCA2, CDKN2A, and TSC1) that were linked to it." (PMID 31900418, 2020). "Significant focal amplifications and deletions, identified by GISTIC2, were evident in regions with known cancer genes, for example, significant focal Cdkn2a deletions (GISTIC q value = 1.39 × 10−5) were evident and EGFRvIII (in Col1a1 locus, GISTIC q value = 0.017) was recurrently amplified." (PMID 32727536, 2020). "The principle CDK4/6 inhibitors lost in cancer are CDKN2A and CDKN2B." (PMID 32242058, 2020). "Analysis of affected individuals belonging to high‐risk pedigrees has long been a powerful design for identification of rare cancer predisposition genes and variants in Utah (e.g., BRCA1 [OMIM 113705], BRCA2 [OMIM 600185], CDKN2A [OMIM 600160], GOLM1 [OMIM 606804], APC, PTEN [OMIM 601728])." (PMID 33118316, 2020). "The cyclin-dependent kinase inhibitor 2A (CDKN2A) gene locus encodes two tumor suppressor proteins, p16Ink4a and Arf, that are key inducers of cellular senescence associated with both aging and cancer." (PMID 33348616, 2020). "However, due to proximity to CDKN2A on Chr9p21, MTAP is co-deleted with CDKN2A in 15-40% of human cancers, resulting in accumulation of unmetabolized MTA and attenuation of endogenous PRMT5 activity." (PMID 32743345, 2020). "MTAP and CDKN2A genes are frequently deleted in human cancers." (PMID 30957015, 2019). "However, they observed that combination of CDKN2A methylation and KRAS mutations independently predicted the risk of recurrence, thereby reducing overall and cancer-specific survival." (PMID 31390840, 2019). "The cell cycle regulating protein, CDKN2A, is frequently inactivated in various cancer types." (PMID 30709382, 2019). "For example, Cdkn2a serves as a cell cycle regulator downstream of Ezh2 in a variety of cancers." (PMID 31259687, 2019). "CDKN2A has been widely reported to act as a potential biomarker, while there were few reports about the cancer risk of abnormal expression of PTCHD3, which definitely shed light on the intensive investigation of PTCHD3 for its role in cancers." (PMID 30704464, 2019). "Among them, 9p21.3 was the only region that covers cancer-related genes, CDKN2A and CDKN2B." (PMID 31235699, 2019). "This analysis was performed to gain experimental evidences on the miRNA functional involvement in cancer mechanisms, where often the growth signals are constitutively activated by a host of mutations (e.g., PIK3CA mutation, HER2 amplification, CDKN2A deletion)." (PMID 29868122, 2018). "In addition, qPCR analysis confirmed homozygous deletions of Cdkn2a and Cdkn2b, another common deletion present in multiple human cancers." (PMID 29925311, 2018).
cancer (continued). "As in other cancers, the loss of cell cycle control plays a prominent role in the pathogenesis in these malignancies that is primarily attributed to loss of CDKN2A (encoding protein p16INK4A)." (PMID 29661169, 2018). "Of note, recurrent homozygous deletions affecting CDKN2A were found in 3/14 (21%) ER-negative adenomyoepitheliomas and, interestingly, these three cases were found to progress to carcinoma (100% versus 9%, P = 0.011, Fisher’s exact test)." (PMID 29739933, 2018). "The most well-studied TSG targets of PcGs are the CDKN2A and CDKN2B loci encoding p14 (ARF), p15 (INK4B) and p16 (INK4A), whose products participate in major tumour suppressor networks that are disabled in human cancer." (PMID 28758948, 2017). "Besides the well-known MPM-associated genes, CDKN2A, NF2 and BAP1, other interesting cancer-associated genes were listed as frequently involved in a copy number loss (e.g. EP300, SETD2 and PBRM1)." (PMID 29371938, 2017). "The cancer syndromes caused by germline mutations in CDKN2A and CDK4 have not been studied to the same degree." (PMID 27804060, 2017). "The CDKN2A locus is among the most common sites of genetic alteration in human cancers." (PMID 28915557, 2017). "Interestingly, we found 23 genes whose expression were significantly altered by SV (P<0.05, unpaired t-test) and among them were well-known cancer-related genes CDKN2A (SV in 5 samples), PRKCA (SV in 3 samples) and EP300 (SV in 3 samples)." (PMID 28548104, 2017). "Hypermethylation of the CDKN2A gene promoter region, resulting in its inactivation, has been reported in several types of malignancy, including lung, head and neck, hepatocellular, breast, and esophageal cancers." (PMID 28637022, 2017). "Our NGS-based approach identified exploitable genomic alterations such as gain-of-function MYD88 oncogene mutations and loss of the tumor suppressor CDKN2A, and thus illuminates new routes to biologically targeted therapies for VRL, a cancer with a dismal prognosis." (PMID 28002793, 2017). "In order to better understand the mechanisms regulating CDKN2A expression, let us consider the mRNA probe A_23_P17356 which had significant associations in breast, but not colon, cancer." (PMID 26860128, 2016). "CDKN2A was a well-established gene, which played a critical role in cancer progression." (PMID 26862903, 2016). "In addition, a subset of the cell lines has mutations in genes that were previously linked to a cancer phenotype, including KRAS (in MDA-MB-231, MIA PaCa-2, Capan-2, AsPC-1, and HCT 116) and CDKN2A (in MCF7, MDA-MB-231, and HCT 116)." (PMID 27630665, 2016). "Given the importance of the Cdkn2a locus in both senescence and cancer, these flanking lncRNAs may offer putative targets to regulate the cell cycle." (PMID 26541291, 2015). "Immunohistochemistry revealed that the cancer cells were diffusely positive for p16 (CDKN2A)." (PMID 26249723, 2015).
cancer (continued). "In addition, our study identified other genes that are frequently hypermethylated in different types of cancer, such as RASSF1a, CDKN2A, hHML1, and CDH1." (PMID 25276247, 2014). "Our results suggest that the cell-type specific depleted signals in cancer cell lines may be under genomic alterations and can be located near genes associated with different types of cancer (i.e. FHIT, STK11, CDKN2A, CDKN2B)." (PMID 25522020, 2014). "Furthermore, CNAs, as often reported in clinical samples, were detected in the regions of some cancer-related genes; for example, copy number gains of FGFR1, EGFR and PDGFRA in H1703, amplification of MYC and a homozygous loss of CDKN2A in LC2/ad." (PMID 25378332, 2014). "The loss of CDKN2A, CDKN1B, and CDKN1A is a predictor of poor prognosis in several types of cancer." (PMID 24605326, 2014). "We did not identify Cdkn2a mutations or copy number alterations in any of the 12 TSAs and eight carcinomas analyzed (data not shown)." (PMID 23845441, 2013). "Also determined, that he frequency of promoter methylation of CDKN2A and MGMT was associated with a 22.9 and 29.1-fold increase in the risk to develop cancer in smoker COPD patients." (PMID 22818553, 2012). "Interestingly, CDKN2A (p16) exhibits more HDs than other recessive cancer genes, and TCR-α genes are located at the deepest HD in lymphoid cells in their dataset." (PMID 23109895, 2012). "Future studies should utilize high-throughputgenotyping methods such as next generation sequencing to account for loss ofheterozygosity in CDKN2A and PTEN, examine therole of T in proliferation, and search for mutations outside ofknown hotspots in cancer genes." (PMID 21602918, 2011). "It is worth noting that CDKN2A, 2B are in strong linkage disequilibrium with rs1412829 at 9p21.3, which has now been identified in 3 independent studies and should therefore be considered an unusually high confidence cancer gene marker." (PMID 21827660, 2011). "The CCND1/CDKN2A assay predicted 5% (1/20) as RB1 (-) cancers." (PMID 21447152, 2011). "These genetic changes include CDKN2A deletion and MYC amplification in immortalization, HRAS activation in transformation, PIK3CA activation in the formation of malignant tumors, and RUNX1 deletion associated with poorly-differentiated malignant tumors." (PMID 20169162, 2010). "These events include CDKN2A deletion and MYC amplification in immortalization, HRAS activation in transformation, PIK3CA activation in the formation of malignant tumors, and RUNX1 deletion associated with poorly-differentiated malignant tumors." (PMID 20169162, 2010). "Additionally, two other well-known recessive cancer genes, CDKN2A and CDKN2B, also had significant p-values, albeit lower rankings (p<0.0025 and FDR = 0.019, respectively)." (PMID 18846217, 2008).
cancer (continued). "Mutation, promoter hypermethylation and loss of heterozygosity involving the tumor suppressor gene p16 (CDKN2a/INK4a) have been detected in a wide variety of human cancers, but much less is known concerning the frequency and spectrum of p16 mutations in premalignant conditions." (PMID 19043591, 2008). "Two high-risk susceptibility genes have been identified (CDKN2A and CDK4) and gene–environment interactions may occur at several steps in cancer development." (PMID 15054457, 2004). "Considerando-se que os genes CDKN2a/p16INK4a, p19ARF e p15INK4b não parecem responsáveis pelas anormalidades observadas, outros genes em 9p21-p22 podem estar envolvidos na etiopatogenia e na progressão dos carcinomas basocelulares." (PMID 15160522, 2004). "No mutations were found and we conclude that CDKN2A mutations do not play a major role in cancer susceptibility in this group." (PMID 11720478, 2001). "However, whether genetic alterations of these genes, including CDKN2A/P16, are coupled with epigenetic changes in cancer development and progression is unknown." (PMID 42192965, 2026). "Notably, the CDKN2A/B deletion is the most frequent CNA across all cancer types." (PMID 41537310, 2026). "This indicates that in certain cases, CCND1 amplification does not necessarily coincide with CDKN2A loss, implying that these two mechanisms may independently contribute to cancer progression." (PMID 40702169, 2025). "Moreover, numerous studies reveal that the CDKN2A locus (encodes the tumor suppressor p16) on chromosome 9p21 is frequently lost in 15% of all cancer cell subsets, and interestingly, the adjacent MTAP locus is co-deleted in 80-90% of these cancer cells." (PMID 41445748, 2025). "We hypothesize that CDKN2A mutations may play a crucial role in tumorigenesis by regulating the cell cycle of tumors and highly expressed CDKN2A may contribute to the malignancy of HNSC by mediating certain cancer-promoting signaling pathways." (PMID 40324259, 2025). "Thus, pan-cancer analysis of CDKN2A ALT may provide new insights into varying prognostic associations involving CDKN2A ALTs among cancer types or show some rationales for different levels of clinical response to ICIs." (PMID 38822443, 2024). "This screen tested palbociclib and abemaciclib against 560 cancer lines and could also not confirm the predictive value in CDKN2A loss/mutation." (PMID 38438376, 2024). "Among them, the olfactory transduction pathway and cytokine receptor interaction pathway was the most common, suggesting that through its participation in in these two key signaling pathways, CDKN2A might have a significant impact on the incidence and progression of different cancers." (PMID 38206516, 2024). "Somatic copy number deletion of the CDKN2A gene is a transformed cell-specific event, which prompted scientists to study whether disruption of the CDKN2A deletion-related feedback regulatory loop may overcome the resistance of P16-inactivated cancer cells to CDK4 inhibitors." (PMID 39351198, 2024).
cancer (continued). "Finally, the data on the gene expression profiles of cancer cell lines were integrated in the Genomics of Drug Sensitivity in Cancer (GDSC) database for drug sensitivity to fully explore the potential value of CDKN2A, DLAT, DLST, GLS, and PDHA1 genes as novel therapeutic targets." (PMID 36891150, 2023). "Thus, we could present a possible mechanism of how Cdkn2a was inactivated in inflammation-related cancer development." (PMID 37845228, 2023). "Additionally, trametinib is also recommended by BRAF and MAP2K1 alterations, as well as new molecular evidence, such as G6PD (mutation and high overexpression), CDKN2A (deletion and underexpression) and due to the genetic dependency of MAP2K1 in BRAF-mutant cancer cell lines." (PMID 37207338, 2023). "The heat map shows the drugs or components that may target CDKN2A in three or more cancer types." (PMID 36961395, 2023). "Therefore, the inactivation of CDKN2A/B may lead to rapid or uncontrolled cell growth and even cancer formation." (PMID 37314514, 2023). "Thus, the Arpc2 floxed Cdkn2a null cells used in our studies present an opportunity to study Arp2/3 complex function in a genetic background that is particularly relevant to preventing the growth of cancer cells." (PMID 36706133, 2023). "Moreover, E2F-targets are also closely related to the expression of CDKN2A in cancer." (PMID 36961395, 2023). "Therefore, it might be of interest to evaluate IHC levels of p16 expression to provide information about CDKN2A alterations in other cancers." (PMID 36900302, 2023). "Given that the family history of patient #32, who had a germline PV in the CDKN2A gene, is unknown, a familial predisposition to these two cancers cannot be ruled out." (PMID 37762649, 2023). "CDKN2A, IKZF1, ETV6, RUNX1, and FLT3 were the top genes mutated in leukemias, while somatic alterations in ALK, NF1, and PTEN primarily occurred in solid tumors, suggesting that the driver alterations are either common to cancer (e.g., cell cycle) or specific to pediatric cancer histotype." (PMID 36845394, 2023). "The International Cancer of the Pancreas Screening Consortium indicates the screening for PDAC onset in patients with Peutz–Jeghers syndrome, with presence of STK11 mutation; with presence of a CDKN2A, BRCA1/2, or MMR mutation and with a first-degree relative affected with PDAC." (PMID 35205366, 2022). "Indeed, prognostic effects of CDKN2A/BHD have been observed in a series of cancers." (PMID 35253368, 2022).